ETV4 (ETS variant transcription factor 4)
Diseases named in the same sentence as ETV4 in open-access papers (continued):
Sharing a sentence is not in itself a finding about the gene and the disease.
small cell lung carcinoma (2 papers, 2021 to 2023). Small cell lung cancer (SCLC) is a highly aggressive malignant neoplasm, accounting for 10-15% of lung cancer cases, characterized byrapid growth, and early metastasis. "(b) Heat map of the PEA3 family ETS transcription factors (ETV1, ETV4, and ETV5) and neuroendocrine transcription factors (ASCL1, NEUROD1, INSM1, and POU3F2 [BRN2]) in small cell lung cancer and lung adenocarcinoma cell lines." (PMID 34121659, 2021).
cervical squamous cell carcinoma (1 paper, 2023). A squamous cell carcinoma arising from the cervical epithelium. "High expression of ETV4 predicted poorer progression-free interval for GBMLGG, ACC, MESO, PCPG, LGG, and cervical squamous cell carcinoma and endocervical adenocarcinoma (CESC), and better progression-free interval for ovarian serous cystadenocarcinoma." (PMID 37205199, 2023).
endometrial tumor (1 paper, 2021). "For example, ETS variant transcription factor 4 (ETV4) holds a potential role in endometrial tumor-specific estrogen receptor binding." (PMID 33179749, 2021).
epilepsy (1 paper, 2021). A brain disorder characterized by episodes of abnormally increased neuronal discharge resulting in transient episodes of sensory or motor neurological dysfunction, or psychic dysfunction. "It should be noted, however, that the ETS expression profile is also different in epilepsy; ELF1, ELK1, ELK4, ETS1, ETS2, and ETV1 are expressed at higher levels than ELF4, ELK3, and ETV4, and there is also variability in expression among different types of epilepsy." (PMID 33671331, 2021).
erectile dysfunction (1 paper, 2022). Persistent or recurrent inability to achieve or to maintain an erection during sexual activity. "Interestingly, Pea3, also known as ETS Variant Transcription Factor 4 (Etv4), has been linked to urological cancers in humans, however, has not been investigated as a cause for erectile dysfunction." (PMID 36301850, 2022).
germ cell tumours (1 paper, 2023). "Six of these genes, including Etv1, Etv4, Ret, Tdgf1, Pdk1 and Calcoco, have been associated with germ cell tumours, stem cells, cell self-renewal, cancer, cell proliferation and cell survival." (PMID 38053127, 2023). "Further examination of the genes that were lower than expected revealed six FGFRi-MEKi DEGs associated with stem cell differentiation, cell self-renewal, cancer, cell proliferation and survival and germ cell tumours, including Etv1 and Etv4, Pdk1, Ret, Tdgf1 and Calcoco2." (PMID 38053127, 2023).
glioneuronal tumors (1 paper, 2025). "In these conditions, ETV4 would be an interesting marker for screening the CIC fusions in the spectrum of high‐grade glial/glioneuronal tumors, IDH, H3‐ and BRAF‐wildtype." (PMID 39442927, 2025).
insulinoma (1 paper, 2021). "Depleting COP1 or DET1 leads to the accumulation of ETV5 and, to a mild extent, ETV4 in MIN6 insulinoma cells, whereas co-expressing COP1 and DET1 diminishes ETV5 levels, suggesting that CRL4COP1/DET1 mediates ETV5 degradation, which is further supported by ETV5 stabilization upon MLN4924 treatment." (PMID 33911083, 2021).
intracerebral hemorrhage (1 paper, 2026). A cerebrovascular disorder characterized by bleeding into one or both cerebral hemispheres including the basal ganglia and the cerebral cortex. "Cell experiments revealed that the inhibition of METTL3 or knockdown of ETV4 can significantly alleviate neuroinflammation and brain tissue damage caused by intracerebral hemorrhage, suggesting a causal relationship between this regulatory axis and disease progression." (PMID 41601663, 2026). "Nevertheless, the functional role of ETV4 in the pathological progression of intracerebral hemorrhage (ICH) remains elusive." (PMID 41601663, 2026).
kidney cancer (1 paper, 2022). Primary or metastatic malignant neoplasm involving the kidney. "We observed that the mRNA expression level of ETV4 was significantly increased and the expression levels of SH2B3, FATE1, GRK5, MALL, HRH2, SEMA3G and SLC10A6 were decreased prominently in kidney cancer cells when compared with HK2 cell line." (PMID 36059531, 2022). "Furthermore, we detected the mRNA and protein expression levels of 8 epi-PCGs (ETV4, SH2B3, FATE1, GRK5, MALL, HRH2, SEMA3G and SLC10A6) in 4 human kidney cancer cell lines (786-O, A498, Caki-1 and ACHN) and the normal human renal tubular epithelial cell line HK2." (PMID 36059531, 2022).
metastatic prostate carcinoma (1 paper, 2018). A carcinoma that arises from the prostate gland and has spread to other anatomic sites. "In a genetically engineered mouse model of metastatic prostate cancer, combined activation of PI3-kinase and Ras signaling could activate ETV4 and leading to promote metastasis." (PMID 29467595, 2018).
Multiple Myeloma (1 paper, 2025). "In Multiple Myeloma, ETV4-dependent transcriptional plasticity can maintain MYC expression and is related to drug resistance." (PMID 41318472, 2025).
oligodendroglioma (1 paper, 2019). A well-differentiated (WHO grade II), diffusely infiltrating neuroglial tumor, typically located in the cerebral hemispheres. "RNAseq data from TCGA identified 221 differentially expressed genes in CIC mutant versus wild-type oligodendrogliomas (fold cutoff of 1.5, p-value < 0.05 and FDR < 10%) amongst which the known CIC targets ETV1, ETV4, and ETV5 were significantly up-regulated in CIC-mutant cases." (PMID 30737375, 2019).
ovarian serous cystadenocarcinoma (1 paper, 2023). A malignant serous cystic epithelial neoplasm arising from the ovary. "ETV4 was positively associated with ploidy in nine tumors and negatively associated with ploidy in GBMLGG, LGG, KIPAN, THCA, and ovarian serous cystadenocarcinoma." (PMID 37205199, 2023).
renal agenesis (1 paper, 2010). Renal agenesis (RA) is a form of renal tract malformation characterized by the complete absence of development of one or both kidneys (unilateral RA or bilateral RA respectively), accompanied by absent ureter(s). "In contrast to Gdnf or Ret mutations, renal agenesis caused by concomitant lack of the transcription factors ETV4 and ETV5 is not rescued by removing Spry1, consistent with their role downstream of both RET and FGFRs." (PMID 20084103, 2010). "Loss of Gdnf causes renal agenesis because in the presence of SPRY1 the level of FGF10 signaling via FGFR2 is not sufficient to produce the necessary responses, such as an appropriate level of Etv4 and Etv5 expression." (PMID 20084103, 2010). "When Spry1 is absent there is no brake on signaling via FGFR2, and GDNF can be removed without causing renal agenesis, due (at least in part) to the effects of FGF10, and to the restoration of Etv4/Etv5 expression; however, UB branching pattern is abnormal." (PMID 20084103, 2010).
skin cutaneous melanoma (1 paper, 2023). "ETV4 was positively associated with MATH in 14 tumors and negatively associated with MATH in GBMLGG, LGG, and skin cutaneous melanoma." (PMID 37205199, 2023).
squamous cell carcinoma (1 paper, 2023). A carcinoma arising from squamous epithelial cells. "This comparison showed an overlap of five genes (ETV4 (tumor non-malignant signature), STK32A, SPINK1, GOLT1A, KRT6A (adenocarcinomas—squamous cell carcinomas signature)) in the first case, and an overlap in one (KRT15) of the three most prominent genes in the second case." (PMID 36832225, 2023).
testicular germ cell tumor (1 paper, 2023). A germ cell tumor arising from the testis. "ETV4 was negatively associated with NEO in LUAD, COAD, COADREAD, testicular germ cell tumors, and CHOL." (PMID 37205199, 2023).
thymoma (1 paper, 2023). A neoplasm arising from the epithelial cells of the thymus. "ETV4 expression was positively related to StromalScore in GBMLGG, PRAD, thymoma, and PCPG, and negatively related to StromalScore in 19 other tumors." (PMID 37205199, 2023).
urothelial carcinoma (1 paper, 2020). A malignant neoplasm derived from the transitional epithelium of the urinary tract (urinary bladder, ureter, urethra, or renal pelvis). "Interestingly, some of these genes, such as ETV4, PTGES, CTBP2, FZD6, EAF2, and IKZF6, have not been implicated in urothelial carcinoma; thus, these genes are potential candidates for diagnostic, prognostic, and therapeutic biomarkers of urothelial carcinoma." (PMID 32391279, 2020).
tumor (136 papers, 2005 to 2026). "E-twenty-six-specific sequence variant transcription factor 4 (ETV4) has also been demonstrated to involve in tumor progressions." (PMID 41318472, 2025). "Positive nuclear ETV4 staining was observed in 49 of 81 (60.49%) tumor tissues, which was positively associated with tumor size, lymph node metastasis, and TNM stage (all p < 0.01)." (PMID 40548893, 2025). "ETV4 has been implicated in carcinogenesis and tumor metastasis, with its deregulated target genes playing a critical role in these processes." (PMID 40469297, 2025). "A 2013 study reported that ELK1, as well as ETS variant transcription factor 4 (ETV4 or PEA3), regulates the expression of the tumor-suppressing microRNA miR-200b." (PMID 40862737, 2025). "In most cases, ETV4 is implicated in carcinogenesis and participates in the process of tumor metastasis." (PMID 40469297, 2025). "Given in the importance of EMT in tumor metastasis, we first explored the association of ETV4 expression and CRC EMT." (PMID 41281746, 2025). "After identifying that ETV4 is negatively associated with the tumor-killing activity of T cells, we proceeded to investigate the underlying mechanism." (PMID 41502516, 2025). "ETV4 regulates chemokine expression to recruit tumour‐associated lymphocytes such as neutrophils, for promoting tumour metastasis and organ colonization." (PMID 39163517, 2024). "ETV4 is known to activate the transcription of multiple tumor-associated genes, including MMP genes, Cox2, Cyclin D3, and Snail, suggesting a role in tumor progression and metastasis." (PMID 29371979, 2017). "Gene expression patterns from human tumor samples were then separated by their similarity to our developed gene signatures associated with loss of ETV4 (shETV4), ACC1 (shACC1) and ACLY (shACLY)." (PMID 26452058, 2015). "The dual role in both tumor metabolism and immune cell recruitment may distinguish ETV4 from other transcription factors associated with immunotherapy resistance." (PMID 41502516, 2025). "Building on previous findings that ETV4 is associated with overall survival (OS) in 10 tumor types, we extended our analysis to the expression of ETV4 across immune subtypes in these and an additional 23 tumor types." (PMID 40469297, 2025). "Therefore, our discovery of ETV4 as a mechanical transducer provides new insights into the mechanisms underlying tumour progression and suppression." (PMID 38702503, 2024). "Indeed, the expression of ETV4 was positively associated with tumor heterogeneity in the majority of cancers studied." (PMID 37205199, 2023). "The reduced expression of ETV4 in MSI tumours could be due to the presence of dinucleotide (GT) repeats in the third intron of the ETV4 gene, causing frame-shift mutation in the coding region owing to its instability." (PMID 34824625, 2021). "Although the related transcription factor ETV4 has been associated with metastasis and tumor progression in other cancers, its role in GIST is unknown." (PMID 29371979, 2017). "ETV4 is known to bind to the enhancer of the adenovirus E1A gene, activate matrix metalloproteinase genes and be associated with invasion and metastasis of tumour cells." (PMID 26238195, 2015). "The overexpression of ETS translocation variant-4 (ETV4) in HCC cells leads to the activation of PD-L1 and CCL2, which consequently results in the recruitment of TAMs and MDSCs to the tumor site." (PMID 40500404, 2025). "Functional assays further confirmed that ETV4 enhances tumor cell proliferation and migration while inhibiting apoptosis, reinforcing its role in tumor progression." (PMID 40469297, 2025). "In contrast, the expression levels of ETV4 or ETV5 in GBM are significantly higher compared to non‐tumour samples only in the Rembrandt database." (PMID 40275610, 2025). "To further validate the role of ETV4 in various cancers, we examined ETV4 expression across multiple tumor cell lines using the CCLE database." (PMID 40469297, 2025).
tumor (continued). "Notable examples within this intersecting group of genes included CDH3, ETV4, ESM1, and KRT80, all previously implicated in CRC progression and tumor microenvironment modulation." (PMID 40722723, 2025). "Collectively, these results suggest that ETV4 expression impairs T cell-mediated tumor killing by downregulating PD-L1 at the transcriptional level, thereby contributing to immune evasion." (PMID 41502516, 2025). "Our results suggest that ETV4 is intricately involved in the immune invasion of tumor cells, impacts patient prognosis, and provides a novel target for drug development." (PMID 40469297, 2025). "Functional studies and murine models were employed to investigate the role of ETV4 in T cell-mediated tumor killing and tumor growth." (PMID 41502516, 2025). "It is reported that ETV4 can promote tumor invasion and metastasis by upregulation of matrix metalloproteinase (MMP)." (PMID 41281746, 2025). "Functional studies demonstrated that ETV4 impairs T cell-mediated tumor killing by transcriptionally upregulating programmed death-ligand 1 (PD-L1)." (PMID 41502516, 2025). "Representative IHC images from the HPA database further illustrate ETV4 protein expression in selected normal tissues and their corresponding tumor counterparts." (PMID 40469297, 2025). "For instance, the Polymoma Virus Enhancer-3 (PEA3) subfamily (e.g., PEA3, ETS Variant Transcription Factor 4 (E1AF), and Erythromycin Resistance Methylases (ERM)) is involved in processes such as cell migration, invasion, and tumor progression." (PMID 40181983, 2025). "CIC-DUX4 fusion leads to the activation of molecular networks involved in tumor growth and metastasis and activates the transcription factor ETV4." (PMID 40427614, 2025). "While our study primarily focused on tumor cell-intrinsic ETV4, its expression in stromal components raises the possibility of off-target effects in future systemic targeting strategies." (PMID 41502516, 2025). "To determine if MCMs/ORC1 participate in ETV4‐regulated tumor growth in vivo, we stably repressed MCMs/ORC1 in the H358‐ETV4 cells by sh‐MCMs or sh‐ORC1 transfection and double antibiotic‐resistant cell selection." (PMID 40548893, 2025). "Collectively, our findings provide new insights into the multifaceted role of ETV4 in tumor biology and immune regulation and lay the groundwork for future studies aimed at validating ETV4 as a biomarker and potential therapeutic target across cancers." (PMID 40469297, 2025). "Coculture of human CD8+ T cells with SK-MEL-28 cells under direct physical contact demonstrated that ETV4 downregulation enhances the in vitro tumor-killing ability of CD8+ T cells." (PMID 41502516, 2025). "Silencing ETV4 resulted in the inhibition of proliferation and cell cycle progression in papillary thyroid cancer cells, and it suppressed tumor growth by inducing ferroptosis." (PMID 39917169, 2025). "Single-cell RNA sequencing (scRNA-seq) was used to dissect the cellular expression and function of ETV4 in the tumor microenvironment." (PMID 41502516, 2025). "Our research demonstrated that ETV4 is highly expressed in 29 different types of cancers, as well as in 18 pairs of matched tumor samples." (PMID 40469297, 2025). "In an orthotopic mouse model, Etv4 knockdown reduced tumor growth and metastasis, suggesting a role in more aggressive disease." (PMID 38916046, 2024). "Our results encompass a range of novel and well-known tumor growth-inhibiting as well as -activating signatures, such as the potential regulation of the ETV4 transcriptional activity by DCN or the PLAU-PLAUR ligand-receptor interaction." (PMID 38200223, 2024). "This includes tumor growth-inhibiting as well as -activating signals, such as the potential regulation of the ETV4 transcriptional activity by DCN or the PLAU-PLAUR ligand-receptor interaction." (PMID 38200223, 2024).
tumor (continued). "The spatial mapping of ETV4 transcriptional activity revealed overall low levels within the tumor, excepting for a region exhibiting invasive morphological traits and higher macrophage infiltration." (PMID 38200223, 2024). "CRISPR knockout of etv4 significantly suppressed tumor formation, suggesting that ETV4 has a cooperative role in CIC::DUX4 tumorigenesis." (PMID 38916046, 2024). "E26 transformation‐specific (ETS) variant 4 (ETV4), an ETS family transcription factor, has been demonstrated to be an accomplice in the metastasis and progression of many tumours and a key factor in patient survival." (PMID 39163517, 2024). "Overall, the findings reveal a novel mechanism of how tumor cells regulate TANs‐induced lymphangiogenesis and LN metastasis and identify ETV4 as a therapeutic target of LN metastasis in BCa." (PMID 36670069, 2023). "To address the putative roles of Cbx6, Trib3, and Etv4 as downstream effectors of the tumor promoting effect of Kdm5c KD, we assessed the consequences of KD of either of them in combination with Kdm5c KD." (PMID 36631623, 2023). "To investigate the function of ETV4 in the tumor microenvironment, we calculated the correlation between ETV4 levels and 60 common immune checkpoint (ICP) genes (36 stimulatory and 24 inhibitory)." (PMID 37205199, 2023). "Because TCGA dataset comprises mainly tumor tissue and very little normal tissue, ETV4 expression was reanalyzed using data from both TCGA and GTEx." (PMID 37205199, 2023). "The biological properties of the putative proteins encoded by the alternative transcripts, which are more frequent in prostate cell lines and in tumor tissues (ETV4 ∆4, ∆6–8, ∆7, and X1) have been investigated in vitro." (PMID 37002241, 2023). "Collectively, cancer cell is the major source of ETV4, at least in BCa, which promoted LN metastasis depending on both TANs‐mediated lymphangiogenesis and tumor‐intrinsic migration and invasion." (PMID 36670069, 2023). "Through bioinformatics analyses and immunohistochemistry arrays of tumor tissue, ETV4 expression was found to be elevated in multiple cancers." (PMID 37205199, 2023). "Consistently, we further observed ETV4 mRNA expression levels positively correlated with CXCL1 or CXCL8 mRNA expression levels in the tumor tissues." (PMID 36670069, 2023). "Expression of ETV4 was also remarkably correlated with immune cell infiltration, tumor heterogeneity, mismatch repair gene expression, DNA methylation, and tumor stemness." (PMID 37205199, 2023). "Several studies in prostate cell lines have shown that ETV4 induces many neoplastic features: invasiveness, cell migration, cell cycle progression, anchorage-independent growth, tumor growth in a xenograft model and also epithelial mesenchymal transition." (PMID 37002241, 2023). "ETV4 belongs to one of the 568 cancer-driven genes, which were revealed by carefully designed bioinformatics methods from approximately 28,000 tumor samples of 66 cancer types." (PMID 35121725, 2022). "From the Oncomine database, multiple tumor types including CRC demonstrated higher ETV4 and ETV5 expression in tumor tissues than those in corresponding normal tissues." (PMID 35860243, 2022). "The mRNA and protein levels of ETV4 are higher in tumor tissues compared with adjacent tissues, and high expression of ETV4 is associated with poor prognosis in HCC patients." (PMID 35121725, 2022). "The ETV4 expression is related to tumor grade, stage, lymph node metastasis and prognosis in HCC patients." (PMID 35121725, 2022). "Previous studies have suggested that ETV4 plays a role in affecting tumor cell migration and invasion through a colony-forming assay by regulating MMP1." (PMID 35121725, 2022).